INS (insulin)
Diseases named in the same sentence as INS in open-access papers (continued):
Sharing a sentence is not in itself a finding about the gene and the disease.
diabetes (continued). "Besides nutrition, other situations that lead to discrimination of adolescents with diabetes are those related to insulin therapy and glycemic control." (PMID 33672506, 2021). "Similarly, using transgenic mice, they demonstrated that overexpression of miR-7 leads to β-cell dedifferentiation, impaired insulin release and, subsequently, diabetes." (PMID 34069422, 2021). "The incurable metabolic condition, diabetes mellitus or diabetes, is attributed to loss or absence of an insulin hormone." (PMID 34462631, 2021). "In addition, recent advances in insulin pump technologies (Hybrid closed-loop systems) target the reduction of such variability and improve overall diabetes control." (PMID 33995287, 2021). "This information will help determine the actual practice of skin disinfection among Japanese patients who self-inject insulin for diabetes, as well as the factors that might influence infection symptoms at the injection site." (PMID 33916158, 2021). "However, studies in type 1 and type 2 diabetes patients have confirmed that, in comparison with conventional therapy, using insulin IT to reduce glycemic levels rapidly can bring about the onset of EWDR." (PMID 33607771, 2021). "Additionally, we found that this peer support intervention that improved diabetes distress was most effective in reducing HbA1c levels in White and insulin-requiring veterans with T2D." (PMID 33427667, 2021). "In addition, studies have demonstrated that PPAR can activate AKT expression, resulting in increased insulin sensitivity and improvement of glucose metabolism in diabetes mellitus." (PMID 33981226, 2021). "Theoretically, a new perspective for future treatments of mutant insulin-related diabetes might be achieved by briefly stimulating mTORC1, given that the stimulation is performed during the neonatal period." (PMID 35141228, 2021). "First, the variables we extracted were limited and lacked information about other diabetes risk factors, such as glycated glycosylated hemoglobin, serum insulin and C-peptide concentration." (PMID 34268283, 2021). "Importantly, the observed increase was most prominent among women with diabetes requiring therapy with insulin (GDMG2/T1DM)." (PMID 33602333, 2021). "This could induce acute impairment of insulin secretion and β cell destruction resulting in de novo diabetes development." (PMID 33995267, 2021). "Where rapid acting insulin is used (to cover glucose rises after meals), estimating carbohydrate loads of the meals, dose-adjusting insulin doses and correcting elevated glucose levels are additional required practices of daily diabetes self-management." (PMID 36994332, 2021). "In the UK Prospective Diabetes Study Group (UKPDS), metformin showed a significant reduction in cardiovascular events (MI and stroke) or all-cause mortality compared with diet or chlorpropamide or insulin." (PMID 34054542, 2021). "Furthermore, a study reported that switching from olanzapine to risperidone for the treatment of schizophrenia exacerbated a patient’s diabetes mellitus and hyperglycemia and resulted in decreased blood glucose levels and increased insulin levels." (PMID 33401717, 2021). "The excess weight combined with hyperglycemia predisposes oxidative stress and inflammation can impair insulin signaling and promote the development of comorbidities, such as type 2 diabetes mellitus (DM2), hypertension, and other factors that induce cardiovascular complications." (PMID 33807959, 2021). "Individualized diabetes management and personalized insulin therapy based on collected dietary information and real-time communication with healthcare professionals, may be achieved by utilizing this novel “smart” technology." (PMID 33918343, 2021).
diabetes (continued). "The literature study revealed that most of the phytochemicals with antidiabetic bioactivity in the plant root system are involved in the management of diabetes through reducing hyperglycemia and hyperlipidemia, α-glucosidase inhibition, and insulin secretion regulation." (PMID 34900828, 2021). "In spite of this strong association of glycine metabolism with diabetes and related conditions, a direct role for glycine in the regulation of insulin sensitivity or glucose homeostasis has not been demonstrated." (PMID 34342168, 2021). "The effect of sitagliptin on reducing BMI and the occurrence of hypoglycemia in obese patients with insulin treatment-induced diabetes mellitus might be correlated with decreased leptin levels and increased adiponectin levels." (PMID 34446063, 2021). "Diabetes encompasses a spectrum of disorders represented most prominently by an inability to properly regulate blood glucose due to an impaired response to utilize insulin, the hormone responsible for transporting glucose from the blood into cells." (PMID 34371888, 2021). "Previous studies have reported that type 2 diabetes mellitus (T2DM) is a risk factor for AD, and an important mechanism may be changes in brain insulin levels." (PMID 33663435, 2021). "Second, the CDM database lacks detailed clinical information on pubertal status, insulin regimen and dosing, use of a diabetes device, and socioeconomic status, which could affect glycemic control and BMI trends." (PMID 34272437, 2021). "Indeed, hepatic insulin clearance is significantly inhibited in T2D patients, thereby synergizing with insulin hypersecretion by pre-diabetes beta cells." (PMID 34659123, 2021). "It has also been suggested that cardiac dysfunction seen in IDCM without diabetes is also associated with both whole-body and myocardial insulin resistance." (PMID 34778146, 2021). "These mice were prone to diabetes, with elevated serum insulin, lipids, and cardiac hypertrophy." (PMID 34631690, 2021). "Among the many therapeutic proteins, insulin plays a key role in the treatment of diabetes." (PMID 33422063, 2021). "These similarities might signify increased duration of the disease process, continuously decreased insulin production, and encouraged incidence of diabetes complications that finally increased blood glucose level." (PMID 33630936, 2021). "Although diabetic patients presented an overall lower survival than those without diabetes, insulin-treated diabetes was not an independent risk factor for higher mortality in a recent analysis." (PMID 34564131, 2021). "The mean time from the diagnosis of diabetes to insulin therapy was 4.15 years." (PMID 34899594, 2021). "This review also reiterates that adipokines play essential roles in satiety, appetite, regulation of fat storage and energy, glucose tolerance, and insulin release, solidifying the important role that adipose tissue plays in the development and pathogenesis of diabetes mellitus." (PMID 34299261, 2021). "Therefore, JDTL exerts good hypoglycemic and insulin secretion-promoting effects that highlight its great potential as an anti-diabetes drug." (PMID 34740995, 2021). "Diabetes can be secondary to the effects of some medications (for examples glucocorticoids and immunosuppressants drugs) that can alter the secretion or action of insulin." (PMID 33810048, 2021). "STAM mice do not become obese, but exhibit the progressive loss of insulin production and development of diabetes mellitus (DM)." (PMID 33802238, 2021). "In addition, pancreatic amylase production is strongly influenced by insulin production, which we know plays a key role in diabetes and metabolic syndrome." (PMID 34444230, 2021). "In particular, mHealth apps for diabetes self-management are promising and proliferating at a very high rate, since diabetes (and in particular T1D) is well suited to smartphone-based support given the use of technology around glucose monitoring, insulin dosing, and carbohydrate counting." (PMID 34647896, 2021).
diabetes (continued). "Additionally, the inverse relationship between adiponectin and incident diabetes was attenuated when further adjusted for the insulin sensitivity index." (PMID 34321008, 2021). "Other types of diabetes rely solely on supplementing the body with external insulin." (PMID 34445786, 2021). "Additionally, the treatment of diabetes encompasses adherence to strict eating guidelines, regular use of antidiabetic drugs and/or insulin, self-monitoring of blood glucose and other long-term treatments, all of which influence patient quality of life." (PMID 34732146, 2021). "Interfering with the production and function of liver insulin could lead to the development of T2DM, and insulin resistance (IR) is inextricably linked with the development of diabetes." (PMID 34884501, 2021). "Besides, Cav1 has exerted its effect on insulin signaling and lipid metabolism within the liver, adipose tissues, and skeletal muscles to influence diabetes development." (PMID 34394002, 2021). "Because muscle is a primary target organ for insulin action and glucose homeostasis then the relative size of the muscle mass is inversely related to insulin resistance, a major component of the mechanism linking muscle mass to mortality via its influence on the development of diabetes." (PMID 33668846, 2021). "Ninety-five of 461 patients had a known history of diabetes (20.61%), with 56 (58.95%) patients on only insulin therapy, 25 (26.32%) on oral antidiabetic agents (including metformin, sulfonylureas and dipeptidyl peptidase 4-inhibitors), and 11 (11.58%) on a combination of insulin and orals." (PMID 33814982, 2021). "Diabetes Mellitus type 1 (DM1) is insulin-dependent and is supposed to be an autoimmune disorder." (PMID 34943445, 2021). "This article discusses the limitations and inconsistencies of the insulin pump eligibility criteria relative to current scientific evidence and proposes workable solutions to address this issue and improve the safety and care of all individuals with diabetes." (PMID 34077674, 2021). "Investigating the collective activity of beta cell populations is gaining attention, primarily because of the increasing amount of data showing that the pathogenesis of diabetes comprises disruptions of regulated collective cellular activity and the consequent disturbance in insulin secretion." (PMID 33833686, 2021). "Diabetes is a chronic disease that occurs when INS, a hormone that regulates blood sugar, is not produced in sufficient quantities by the pancreas (type-1 diabetes) or when the body is unable to effectively sense the INS it produces (type-2 diabetes)." (PMID 34884971, 2021). "Diabetes is a group of metabolic disorders that is characterized mainly by elevated levels of glucose in blood (hyperglycemia) and insufficiency in production or action of insulin." (PMID 35050980, 2021). "Currently, the treatment for insulin-dependent diabetes mellitus patients mainly involves obtaining a normal blood glucose value (below 8.0 mmol/L prior to large meals for adult diabetes patients) by delivery of exogenous insulin via conventional injection pen or insulin pump multiple times per day." (PMID 34630098, 2021). "In summary, we showed that STZ administration produced a significant increase in blood glucose level and reduction of body weight, along with other typical symptoms of diabetes, including polydipsia, polyphagia, and polyuria, which were partially reversed by insulin treatment." (PMID 34060586, 2021). "Adequate knowledge and attitude about insulin self-administration could also improve the management of diabetes and eventually improve the quality of life." (PMID 33556090, 2021). "Diabetes mellitus (DM) is a common metabolic illness defined by hyperglycemia caused by insufficient production or absent of pancreatic insulin, with or without concomitant insulin action impairment." (PMID 35655910, 2021).
diabetes (continued). "Some factors impacting insulin doses, such as history and risk of hypoglycaemia, duration of diabetes were not evaluated." (PMID 33099763, 2021). "When asked about how diabetes could be kept under control, the vast majority (90.9%) of the patients could identify medications including insulin." (PMID 33750352, 2021). "Finally, the results showed the potential of DCF and INDO as a drug absorption enhancer in the development of the oral administration of insulin for diabetes patients." (PMID 33806674, 2021). "Insulin therapies were immediately started once diabetes was diagnosed." (PMID 34112266, 2021). "The data suggest that the concurrence of an anti-inflammatory profile, increased insulin sensitivity and polyunsaturated fatty acids content in the hypothalamus may slow down or delay the onset of diabetes." (PMID 34440853, 2021). "The different insulin secretion between long and short diabetes duration might be the reason, which was observed in our study either." (PMID 35111074, 2021). "In addition, exosome-miRNAs are emerging as essential regulators in the progression of diabetes, principally for pancreatic β-cell injury and insulin resistance." (PMID 34959658, 2021). "In addition, diabetic patients in East Asia, including Korea, have a relatively severe decrease in insulin secretion, making it difficult to distinguish diabetes types." (PMID 34199839, 2021). "At present, neither oral hypoglycemic drugs nor insulin is a cure for diabetes; these treatments increase the risk of complications, such as hypoglycemia, gastrointestinal intolerance, heart failure, and atypical fractures." (PMID 33957998, 2021). "However, its use is accompanied by hypoglycemia episodes; long-acting insulin therapy is a safe and effective way of treating diabetes mellitus." (PMID 34345540, 2021). "In addition, the long duration of diabetes and insulin treatment in Patient #1 were actually predictors of poorer glycemic response to high-dose liraglutide." (PMID 35076486, 2021). "However, ACTH administration was associated with significant adverse effects: one patient developed diabetes mellitus in need of insulin treatment, one crusted scabies and the remaining two had regular episodes of mild hypokalemia." (PMID 33498160, 2021). "Diabetes is characterized by chronically elevated blood glucose levels as a result of an inability of the beta cells of the pancreas to generate enough insulin or inefficient insulin use by body cells." (PMID 34513443, 2021). "Insulin is often necessary to attain glycemic targets in the long-term management of diabetes." (PMID 34165382, 2021). "The increased breast density was associated with long-term insulin use (>5 years), and women with diabetes treated with non-insulin agents had lower density." (PMID 33803201, 2021). "Furthermore, we analyzed the effect on weight gain, blood glucose levels, and serum parameters including insulin, in rats with streptozotocin-induced diabetes." (PMID 34083930, 2021). "Attributes of diabetes technologies approved for insulin delivery." (PMID 34184589, 2021). "Moreover, the study results corroborate prior research indicating that patients with younger age at diagnosis, longer duration of diabetes, and insulin therapy are more likely to develop poor mental health and quality of life." (PMID 34646639, 2021). "Caregivers help people with diabetes keep medication schedules, doctor appointments, blood sugar levels, exercise activities, dietary control, insulin administration, record glucose readings, check toenails, observe oral problems, and other health complications." (PMID 33628230, 2021). "Worsening diabetes control was the primary outcome, defined as: 1) HbA1c rose to 58 mmol/mol or higher; 2) HbA1c increase by 10 mmol/mol or more; 3) Start of antidiabetic drugs or switch to insulin." (PMID 34809595, 2021).
diabetes (continued). "Insulin, glucose, norepinephrine, Ang II, aldosterone (which is increased in hypertension), and some adipokines (which are increased in diabetes and obesity) cause prolonged NHE activation in patients with hypertension, diabetes, and obesity." (PMID 34285709, 2021). "Meanwhile, the correlation between BDNF and insulin in different diabetes duration was analyzed." (PMID 35111074, 2021). "Insulin function in diabetics and its subsequent resistance or sensitivity to insulin are the cases that, despite significant research and success in this field, many aspects of it, especially in post-receptor defects, have not been fully identified for the medical research." (PMID 33546744, 2021). "Sudden reduction in insulin sensitivity can precipitate diabetes in individuals with borderline beta-cell function and may even manifest as hyperglycemic crises in those with previously undiagnosed (and untreated) diabetes." (PMID 34163019, 2021). "Regarding the significant correlation of betatrophin with the insulin levels in our study, these findings are important as they may explain the increased frequency of diabetes along with the course of NAFLD." (PMID 34203342, 2021). "The function of the insulin-producing β-cell within the islet is disrupted in diabetes." (PMID 33939712, 2021). "These genes as well as other genes whose expression level in insulin-sensitive tissues correlated with the T2D-associated SNPs of GSS and GGT7 genes are both linked to the pathogenesis of diabetes and represent the arms of a common metabolic pathway-unfolded protein response." (PMID 34575035, 2021). "Furthermore, miR-484 targets the mitochondrial fission gene Fis1, and since mitochondrial fission is increased during diabetes and contributes to circulating insulin levels, downregulation of miR-84 drives the pathogenesis of IR." (PMID 34776961, 2021). "The independent variables were the following: age, education level, possession of the healthcare education, diabetes duration (years), duration of insulin treatment (years), self-assessed three-month A1C level (mmol/L) and frequency of insulin administration per day." (PMID 33561956, 2021). "In support of the hypothesis that lysosome dysfunction may be involved in diabetes pathogenesis, genetic knockout of a key isoform of the vacuolar type H+ ATPase that is present on lysosomes also led to impaired mouse insulin secretion." (PMID 33515072, 2021). "Fasting glucose and insulin levels are critical predictors of diabetes." (PMID 34682732, 2021). "Regardless of the underlying reasons, withholding insulin results in ketoacidosis, a condition that causes various complications in the body, especially when persisting for a long time." (PMID 34371885, 2021). "Nevertheless, some studies of patients who self-inject insulin for diabetes have suggested that the risk of infection is not increased in the absence of skin preparation." (PMID 33916158, 2021). "Third, the effects of other diabetes therapy including insulin, sulfonylurea and glucagon‐like peptide‐1 receptor agonists on pancreatic fat and liver fat accumulations could not be excluded." (PMID 34123402, 2021). "The uniqueness of the Mediterranean diet lies in the ease with which its main components sustain diabetes homeostasis, whether by improving insulin sensitivity and the gut microbiome, or by stimulating anti-inflammatory and antioxidant actions." (PMID 33920947, 2021). "Diabetes is a chronic non-communicable disease (NCD) caused by a malfunction in the formation of insulin in the pancreas or by the ineffective use of insulin produced by the body." (PMID 34946417, 2021). "Several studies have revealed that PP cells on the periphery of the islets protect beta cells in the centre, while decreased PP production may be a sign of reduced insulin production and can be used to predict the development of diabetes." (PMID 34566890, 2021).